KCNQ3 (potassium voltage-gated channel subfamily Q member 3)
Description:
Pore-forming subunit of the voltage-gated potassium (Kv) M-channel which is responsible for the M-current, a key controller of neuronal excitability. M-channel is composed of pore-forming subunits KCNQ2 and KCNQ3 assembled as heterotetramers. The native M-current has a slowly activating and deactivating potassium conductance which plays a critical role in determining the subthreshold electrical excitability of neurons as well as the responsiveness to synaptic inputs. M-channel is selectively permeable in vitro to other cations besides potassium, in decreasing order of affinity K(+) > Rb(+) > Cs(+) > Na(+). M-channel association with SLC5A3/SMIT1 alters channel ion selectivity, increasing Na(+) and Cs(+) permeation relative to K(+). Suppressed by activation of M1 muscarinic acetylcholine receptors. KCNQ3 also associates with KCNQ5 to form a functional channel in vitro and may also contribute to the M-current in brain.
Synonyms: Kv7.3; BFNC2; EBN2
Tractability: Small molecule: an approved drug acts on it; a high-quality ligand is known; it belongs to a druggable protein family. Antibody: UniProt places it where antibodies can reach, with high confidence; its Gene Ontology location is reachable by antibodies, with high confidence; UniProt predicts a signal peptide or a membrane-spanning region. PROTAC: UniProt records ubiquitination sites on it; a small molecule that binds it is known.
Target class: Potassium channels; Ion channel; Voltage-gated ion channel; Voltage-gated potassium channel
Gene: Protein-coding gene on chromosome 8 (132,120,861 to 132,481,095, reverse strand). Ensembl gene ENSG00000184156.
Subcellular location: Cell membrane
Pathways (Reactome):
Developmental Biology: Interaction between L1 and Ankyrins
Neuronal System: Voltage gated Potassium channels
Gene Ontology:
Molecular function: calmodulin binding; protein binding; voltage-gated monoatomic cation channel activity; voltage-gated potassium channel activity; monoatomic ion channel activity; potassium channel activity; voltage-gated monoatomic ion channel activity
Biological process: potassium ion transmembrane transport; chemical synaptic transmission; monoatomic ion transport; potassium ion transport; transmembrane transport
Cellular component: plasma membrane; voltage-gated potassium channel complex; axon initial segment; node of Ranvier; cell surface; membrane; synapse
Genetic constraint (gnomAD): Loss-of-function variants: 27 observed, 81.3 expected, observed/expected ratio (o/e) 0.33, 90% interval 0.24 to 0.46. The upper end of that interval is the gene's LOEUF score, 0.46, which puts it in group 2 of 6, group 1 being the genes least tolerant of losing a copy. Missense variants: 895 observed, 1,110.8 expected, observed/expected ratio (o/e) 0.81, 90% interval 0.76 to 0.85. Synonymous variants: 442 observed, 457.02 expected, observed/expected ratio (o/e) 0.97, 90% interval 0.89 to 1.05.
Gene-disease validity (ClinGen):
ClinGen rates the evidence that KCNQ3 causes each of these diseases.
complex neurodevelopmental disorder (autosomal dominant): Definitive. A disorder that involves more than one phenotype associated with the central nervous system, including but not limited to intellectual disability, autism, and seizures (epilepsy).
genetic developmental and epileptic encephalopathy (autosomal recessive): Limited. A complex neurodevelopmental disorder characterized by a range of developmental delays and epileptic encephalopathy phenotypes.
Homologues: Orthologues: macaque KCNQ3 (99% identical), chimpanzee KCNQ3 (96% identical), mouse Kcnq3 (96% identical), dog KCNQ3 (95% identical), pig KCNQ3 (94% identical), guinea pig KCNQ3 (94% identical), rat Kcnq3 (92% identical), rabbit KCNQ3 (88% identical), tropical clawed frog kcnq3 (72% identical), zebrafish kcnq3 (35% identical). Paralogues in human: KCNQ2 (47% identical), KCNQ5 (41% identical), KCNQ4 (35% identical), KCNQ1 (27% identical), KCNB2 (14% identical), KCNC4 (12% identical), KCNC2 (11% identical), KCNC3 (11% identical), KCND1 (11% identical), KCND2 (11% identical), KCNC1 (10% identical), and 19 more.
Diseases named in the same sentence as KCNQ3 in open-access papers:
KCNQ3 is named in the same sentence as 75 diseases in open-access papers, as found by Europe PMC text mining. Sharing a sentence is not in itself a finding about the gene and the disease. The quoted sentences say what the papers report.
epilepsy (64 papers, 2009 to 2025). A brain disorder characterized by episodes of abnormally increased neuronal discharge resulting in transient episodes of sensory or motor neurological dysfunction, or psychic dysfunction. "KCNQ2 and KCNQ3 play a critical role in modulating susceptibility to seizures, and their mutations cause heterogeneous epilepsy phenotypes." (PMID 41155561, 2025). "KCNQ3-related pathogenic variants comprise self-limited familial neonatal epilepsy and self-limited familial infantile epilepsy, seizure disorders that occur in children who typically have normal psychomotor development." (PMID 39175503, 2024). "KCNQ3 gain-of-function mutations are associated with neurodevelopmental disorders such as severe paediatric epilepsy and autism." (PMID 38398114, 2024). "Recent studies have shown that complete loss of KCNQ3 channel function can lead to pharmaco-dependent epilepsy and intellectual disability." (PMID 33863780, 2021). "Mutations of the KCNQ2 and KCNQ3 voltage‐gated potassium channel genes have been implicated in the pathophysiology of a spectrum of seizure disorders, ranging from pharmacoresponsive self‐limiting neonatal epilepsy to severe epileptic encephalopathy." (PMID 33336127, 2020). "A 114 gene epilepsy panel through the clinical commercial laboratory CeGAT identified a variant of uncertain significance in KCNQ3, c.938C>T, p.Thr313Ile (NM_004519)." (PMID 33336127, 2020). "In the present manuscript, we report the clinical, molecular and functional properties of a BFNE family carrying a novel KCNQ3 variant (c.719T>G; p.M240R) segregating with epilepsy in the three affected individuals." (PMID 33013448, 2020). "On the other hand, a variation of KCNQ3 gene mapped to chromosome 8q24, encoding the voltage‐gated potassium channel Kv7.3, has been linked to epilepsy." (PMID 29934975, 2018). "Further, hypomorphic mutations in either KCNQ2, an established epilepsy-associated gene, or KCNQ3 are reported to be highly penetrant." (PMID 30148849, 2018). "Mutations in KCNQ2 and KCNQ3 subunits underlie various forms of epilepsy, including early infantile epileptic encephalopathy, benign familial neonatal seizures, and other miscellaneous early onset encephalopathies." (PMID 30242262, 2018). "Two other loci, both human epilepsy-associated genes, though insignificant, had lower p-values: KCNQ3 at 0.077 and LGI1 at 0.070." (PMID 21518446, 2011). "Some variants of KCNQ3 that alter channel function have been linked to some rare forms of epilepsy." (PMID 40727427, 2025). "Regarding seizures, the KCNQ3 gene, which codes the Kv7.3 channel, is a prominent candidate since the abnormal discharge of brain neurons represents the foremost feature associated with epilepsy." (PMID 39062689, 2024). "Because of their fundamental role in regulating cellular excitability, this channel in its heterotetrameric form with KCNQ3 is implicated in several human disease conditions, including epilepsy, pain, migraine, arrhythmias, sensory dysfunction, and metabolic illnesses." (PMID 35309507, 2022). "Loss of function of KCNQ2 or KCNQ3 causes epilepsy in humans and mice." (PMID 35188099, 2022). "Importantly, de novo dominant mutations in their neuronal subunits KCNQ2/Kv7.2 and KCNQ3/Kv7.3 are associated with epilepsy and neurodevelopmental disorder characterized by developmental delay and intellectual disability." (PMID 33071824, 2020). "Importantly, >300 dominant mutations in KCNQ2 and KCNQ3 cause epilepsy including benign familial neonatal epilepsy (BFNE) and epileptic encephalopathy (EE; Rikee and ClinVar database)." (PMID 33071824, 2020). "Mutations in the SCN1A gene are a major cause of severe epilepsy in infants, while mutations in KCNQ2 and KCNQ3 genes increase neuronal excitability, affecting seizure frequency and type." (PMID 40520613, 2025). "In this case, the occurrence of epilepsy in a patient was apparently related to the KCNQ3 gene located within the 8q24.23-q24.3 duplication." (PMID 39152504, 2024).
epilepsy (continued). "The other lncRNA is growth arrest-specific 5 (GAS5) which was deregulated in neuronal diseases like epilepsy and its silencing prohibited the KCNQ3 expression via miR-135a-5p sponging to block the epilepsy progression." (PMID 37620425, 2023). "Given that developmental and behavioral impairments in DEE patients exist independently of epilepsy onset, the relationship between KCNQ3 and developmental disorders is an important question to consider." (PMID 37497102, 2023). "Epilepsy caused by the KCNQ2, KCNQ3, PRRT2, SCN2A and SCN8A gene are relatively benign with mild symptoms and consequences." (PMID 35571021, 2022). "Although epilepsy caused by the KCNQ2, KCNQ3, PRRT2, SCN2A and SCN8A gene are relatively benign, in our study, more than 18 genes caused epilepsy accompanied by the intellectual disability and more than 14 genes caused syndromes with epilepsy." (PMID 35571021, 2022). "It has been suggested that neonates with KCNQ2, KCNQ3 or SCN2a epilepsy respond well to treatment with low-dose sodium channel blockers, such as carbamazepine or oxcarbazepine." (PMID 33670692, 2021). "Accordingly, KCNQ3 and KCNQ5 (OMIM 607357) are suggestive susceptibility genes for ASD, ID, major depression, epilepsy, and due to the considerable overlap in etiologies also for other psychiatric disorders like ADHD, bipolar disorder, and anxiety disorder." (PMID 23596459, 2013). "Our model adds to the growing list of other specific human epilepsy knockin mice, including the Gabrg2, Kcnq2, Kcnq3, Scn1a and Chrna4 mice, to report a clear-cut genotype to phenotype seizure susceptibility." (PMID 19763161, 2009). "We next tested whether a correlation between sex hormones and mRNA association with the RISC could also be observed for other voltage-gated potassium channels involved in epilepsy, using Kcnq2 and Kcnq3 (called Kv7.2 and Kv7.3, respectively) as examples." (PMID 37433683, 2023). "For example, KCNQ2, KCNQ3, SCN1A, SCN2A, and SCN8A are associated with phenotypes ranging from self-limited epilepsies with normal developmental outcome to intermediate severity conditions to drug-resistant epilepsies with profound developmental impairment." (PMID 37596007, 2023). "These cells share neuronal genes expressed in central excitatory neurons such as Kcna1, Kcnq2, Kcnq3, Scn1a, Scn8a, genes that are relevant to epilepsy." (PMID 36192157, 2022). "After searching in DrugBank, we retrieved a total of 47 anti-epileptic drugs and 151 targets, of which identified 17 target genes (CACNA1A, CHRNA4,CHRNA7,GABRA1,GABRA2,GABRB2,GABRG2,GRIK1,GRIN1,GRIN2B,KCNQ2,KCNQ3,SCN1A,SCN2A, SCN3A,SCN8A and SCN9A) were overlapped with risk genes of epilepsy." (PMID 36006933, 2022). "A mother who transmitted a severe missense variant (p.Arg330Leu) in KCNQ3 was diagnosed with epilepsy but no cognitive impairment." (PMID 33004838, 2020). "Interestingly, increasing evidence has shown that the gain of function in potassium channel variants is actually associated with epilepsy, including KCNQ2 and KCNQ3." (PMID 31652643, 2019). "This may suggest that, although CACNA1A contributes to epilepsy mutational load, the noise from other pathway-related genes (CHRNA4, KCNQ2, KCNQ3 and PLCB1) compromises this effect." (PMID 27984588, 2016). "This would be advantageous because KCNQ2/KCNQ3 channels have been the focus of extensive pharmacologic research in relation to epilepsy, and several compounds that act either as activators or inhibitors of the complex have already been identified and are in various stages of clinical investigation." (PMID 23730306, 2013). "Our results suggest that dysfunction of the heteromeric KV7.3/5 channel is implicated in the pathogenesis of some forms of autism spectrum disorders, epilepsy, and possibly other psychiatric disorders and therefore, KCNQ3 and KCNQ5 are suggested as candidate genes for these disorders." (PMID 23596459, 2013).
epilepsy (continued). "In addition, we observed some downregulated genes (such as MPZ, GJB1, CDH15, KCNQ3, and PLP1) in K-NSC cells, and abnormal expression of these genes has been reported to cause cognitive impairment, epilepsy, spasticity, and myelin abnormalities, which are similar to the disease symptoms of GLD." (PMID 37076788, 2023). "A considerable proportion of patients with these types of epilepsies also have ID and/or behavioral problems (ADHD, ASD, anxiety, depression) which supports a common genetic etiology and accordingly suggest KCNQ3 (and KCNQ2) as candidate susceptibility genes for ID and various psychiatric disorders." (PMID 23596459, 2013). "Considering that KCNQ2 and KCNQ3 turned out to directly contributing to the initiation and progression of epilepsy, our predicted genes ANK1 and ANK2 as the functional components of ankyrins may very probably be epilepsy associated genes, validating our prediction." (PMID 28255556, 2017). "Additional KCNQ3-related neurodevelopmental disorders with and without epilepsy have also been described." (PMID 39175503, 2024). "Recent work has shown that KCNQ3 dysfunction leads to pharmaco-dependent epilepsy in patients lacking both functional Kcnq3 copies, which is distinct from the pharmaco-resistant epilepsy caused by KCNQ2 dominant-negative variants." (PMID 33863780, 2021). "Since the SNP in KCNQ3 was inherited from a father and a paternal grandmother without neurological abnormalities the authors suggested that the SNP was not responsible for the observed epilepsy." (PMID 23596459, 2013). "In addition, de novo variants in KCNQ3 have been rarely described in children with DEE, intellectual disability (ID) apparently without epilepsy, cortical visual impairment, and in patients with ID and autism." (PMID 33013448, 2020). "However, our understanding of the cellular mechanisms that may both explain the origins of epilepsy and inform treatment strategies for KCNQ2 and KCNQ3 dysfunction is still lacking." (PMID 33863780, 2021).
Epileptic encephalopathy (13 papers, 2015 to 2026). A condition in which epileptiform abnormalities are believed to contribute to the progressive disturbance in cerebral function. "KCNQ2 and KCNQ3 gene mutations usually lead to BNFE or to more severe epileptic encephalopathies." (PMID 38003469, 2023).
autism (11 papers, 2013 to 2024). Persistent deficits in social interaction and communication and interaction as well as a markedly restricted repertoire of activity and interest as well as repetitive patterns of behavior. "KCNQ2 and KCNQ3 gene mutations have been identified in different epilepsy syndromes and, moreover, KCNQ3 gain-of-function variant have been related to autism and developmental disability." (PMID 32676036, 2020). "In line with this hypothesis we here demonstrate different KCNQ3 alterations (truncating mutation, rare SNP with abnormal electrophysiological profile) in four patients with childhood autism and in one transmitting parent with major depression." (PMID 23596459, 2013). "(S) Log-normalized counts of transcripts for the autism-related transcription factor Auts2 and several neurotransmitter receptor and ion channel genes whose expression changes across postnatal development (Glra1, Grin2b, Kcnj3, and Kcnq3)." (PMID 36876911, 2023). "Moreover, the candidate genes PAK3, OCRL, DCX, PTK2, KCNQ3, SOX3, and LAMA1 were associated with autism, brain disease, Dent disease, and other conditions that present ID as a hallmark, corroborating our findings." (PMID 33922640, 2021). "GoF variants in KCNQ2 and KCNQ3 genes were recently reported to cause profound developmental delay, neonatal non-epileptic myoclonus, and later-onset epilepsy such as infantile spasms or the autism phenotype with no clinical seizures, respectively." (PMID 39175503, 2024). "In addition, GoF variants in the KCNQ3 gene were described, causing a phenotype with autism and epileptic discharges on EEG during sleep, but no clinical seizures." (PMID 39175503, 2024). "Another atypical clinical picture was manifested by a patient bearing the mutation c.688C > T (p.(Arg230Cys)) in KCNQ3, who did not suffer from any status epilepticus but showing ID, autism, stereotypies, aggressiveness, bladder anomalies; he also presented craniofacial dysmorphisms (patient #18)." (PMID 34356170, 2021).
depression (7 papers, 2013 to 2025). "Gene therapy directed to elicit overexpression of KCNQ3 in dopaminergic neurons of the ventral tegmental area and the administration of ezogabine (retigabine) locally and systemically normalized depression-like behaviors and neural hyperactivity." (PMID 32120974, 2020). "Supporting evidence of the role of KCNQ3 in resilience was found in a preclinical study that used a social defeat stress model of depression." (PMID 32120974, 2020). "Multiple aspects of these processes are implicated in the development of anxiety and depression in CCH, including aberrant GABA and glutamate signaling, reduced BDNF, impaired synaptic potentiation, changes in synaptophysin, serotonin, and HCN1, as well as reduced dopamine and KCNQ3 activity." (PMID 39851502, 2025). "The overexpression of KCNQ3 (Kv7.3) channels or local infusion of KCNQ opener ezogabine (also known as retigabine, selective for KCNQ2/3 subunits) in the VTA inhibited the increased firing rate of VTA dopamine neurons in susceptible mice and rescued depression-like behaviors." (PMID 38612683, 2024). "Uniquely, the decrease in CNPase and synaptophysin in the white matter mediate an impairment of synaptic potentiation and in anxiety and depression, alongside the upregulation of HCN1 and downregulation of KCNQ3 in the amygdala." (PMID 39851502, 2025). "We applied two drugs to KCNQ3 OE and WT OE33 cell lines, the KCNQ-specific inhibitor linopirdine, and the more broad inhibitor amitriptyline, which inhibits a large number of proteins including KCNQ3, is FDA-approved, and is clinically available to treat depression." (PMID 37748809, 2023).
Intellectual disability (7 papers, 2019 to 2024). "The aim of this work was to report the clinical, molecular, and functional properties of a new KCNQ3 variant found in homozygous configuration in a 9‐year‐old girl with pharmacodependent neonatal‐onset epilepsy and non‐syndromic intellectual disability." (PMID 31440727, 2019). "The present results indicate that a homozygous KCNQ3 loss‐of‐function variant is responsible for a severe phenotype characterized by neonatal‐onset pharmacodependent seizures, with developmental delay and intellectual disability." (PMID 31440727, 2019). "Like many other channelopathies, the phenotypic spectrum now also includes severe epilepsies, including families with drug-resistant seizures and intellectual disability harboring inherited mutations of KCNQ2 and KCNQ3." (PMID 34842787, 2021). "KCNQ3-related encephalopathy is similarly characterized by early onset drug-resistant seizures, centrotemporal EEG abnormalities, and intellectual disability at long-term." (PMID 34842787, 2021). "Interestingly, two of the top DMGs, potassium voltage-gated channel subfamily Q member 3 (KCNQ3) and ubiquitin conjugating enzyme E2 H (UBE2H), were genes in the SFARI database and were enriched in the gene regulatory network related to ASD and mental retardation." (PMID 35978033, 2022).